NQO1 (NAD(P)H quinone dehydrogenase 1)
Diseases named in the same sentence as NQO1 in open-access papers (continued):
Sharing a sentence is not in itself a finding about the gene and the disease.
tumor (continued). "To assess the effects of low RTA 405 concentrations, we measured NQO1 mRNA levels and survival in cell lines treated with 100 to 125 nM RTA 405—doses of RTA 405 that increase NRF2 activity, but do not directly reduce growth of tumor cells." (PMID 26301506, 2015). "We have not been able to directly compare NQO1 levels in cell lines and OSCC tumour tissue, but in vivo expression may well not be as high as that observed in the cultured cell lines." (PMID 24886060, 2014).
infection (35 papers, 2011 to 2025). The state of being infected such as from the introduction of a foreign agent such as serum, vaccine, antigenic substance or organism. "NF-κBp65 phosphorylation was significantly increased as early as 5 minutes after BCG uptake and remained elevated up to 24 h post-infection in NQO1-deficient compared to control cells." (PMID 27297123, 2016). "Though our study was not designed to test dose response or pre-existing “deficiency” of antioxidants, the impact of BSH on expression of HMOX1 and NQO1 after infection may have been linked to baseline levels, i.e. the lower the starting levels of expression, the greater the impact." (PMID 24910991, 2014). "The mRNA transcription level of antioxidant downstream genes Quinone oxidoreductase 1 (NQO1) decreased (p < 0.05) after DK/212 infection." (PMID 38542289, 2024). "Our data demonstrated that the mRNA and protein expression of Nrf2, HO-1, and NQO1 were increased in IPEC-J2 cells after ROS scavenging in the presence of TGEV infection." (PMID 36139913, 2022). "The infection also up-regulated the detoxification and drug metabolism proteins NQO1 and GSTP (respectively)." (PMID 34146958, 2021). "We also compared expression of NRF2-target genes, Hmox1 and Nqo1, in WT and Tlr3-/- cells at 8 hrs post-infection." (PMID 33765083, 2021). "Induction accompanied by nuclear enrichment of Nrf2 was further transduced to the transient transcriptional boost followed by a modest protein level accumulation of Nrf2-driven targets such as HO-1 and NQO1 at initial hours of infection (3 hpi)." (PMID 32322337, 2020). "IV infection can decrease the production of antioxidation targets, such as HO-1 and NQO1, SOD1, GR, CAT, and GPx1 are downstream molecules of the Nrf2 pathway after IV infection." (PMID 32689931, 2020). "Western blot results have revealed that single infection with T. spiralis alone had negligible effects on Nrf2, NF-κB, phospho-p65, although a noticeable increase in NQO1 was observed." (PMID 32466130, 2020). "Infection with Mabs alone led to a weak induction of HO-1 mRNA or an induction of NQO1 mRNA that decreased 6 h after Mabs infection." (PMID 27551455, 2015). "Real-time RT-PCR analysis also showed that KSHV infection of shRL cells induced NQO1 mRNA to a significantly higher extent than during the infection of shNrf2 cells (compare black and red bars)." (PMID 25340789, 2014). "Infection of shNrf2 cells, on the other hand, revealed significantly lower basal and induced NQO1 levels (third panel)." (PMID 25340789, 2014). "Throughout the infection, immunostaining of NQO1 was localized within the PLF regions of the lungs where NQO1 expression overlapped with the high Nrf2 expression levels." (PMID 22028843, 2011). "NQO1 expression decreased as the infection progressed which inversely correlated with increased Nrf2 cytoplasmic expression over time (r = −0.96)." (PMID 22028843, 2011). "Airway epithelium, vascular endothelium and alveolar macrophages consistently expressed NQO1 in the early stages of infection (days 5, 15 and 20)." (PMID 22028843, 2011). "Further confirming that CDDO-Me induced Nrf2 pathway activation in a Nrf2-dependent manner, N2a cells that had been pretreated with the Nrf2 inhibitor ATRA before CDDO-Me treatment and SC16 infection showed significantly decreased Nrf2, HO-1 and NQO1 expression (P < 0.01)." (PMID 37950261, 2023). "Notably, the levels of HO-1 and NQO1 increased markedly in CDDO-Me-treated N2a cells upon infection with RABV strains of differing virulence." (PMID 37950261, 2023). "Analysis of lung homogenates or BAL in a mouse model of RSV infection also showed a decline in the active levels of SOD 1-3, catalase, glutathione peroxidase (GPx), GST, peroxiredoxin (Prx) 6, heme oxygenase 1 (OH-1) and NAD(P)H:quinone oxidoreductase (NQO1) at a late time of infection." (PMID 27187445, 2016).
infection (continued). "In addition, the mRNA expression levels of NQO1 and HO-1 in jejunum showed a downward trend, but the mRNA expression level of the HO-1 gene had no statistical significance compared with the S. typhimurium C7731 infection group." (PMID 38930517, 2024). "Furthermore, infection reduced Nrf2 and NAD(P)H quinone dehydrogenase 1 (NQO1)." (PMID 38731952, 2024). "Interestingly, inhibition of NQO1 using dicoumarol abolished sulforaphane effect on Mabs growth and cording in CF context, indicating that NQO1 might play a protective role during Mabs infection." (PMID 37619220, 2023). "The protein expression levels of Nrf2, Ho-1, and Nqo1 genes in SVA-infected cells at 6 h and 4 h after infection were significantly increased." (PMID 40266921, 2025). "As observed in Nrf2-/- mice, dKO mice presented greater ROS levels at week 6 post-infection and less expression of NRF2-target genes Hmox1 and Nqo1 as measured at week 3 post-infection on total footpad lesions caused by LgyLRV1+ parasites." (PMID 33765083, 2021). "We quantified the protein expression of NQO1, GPX1, Prdx1, HO-1, and HO-2 during the course of infection." (PMID 32669339, 2020). "Cells with larger amounts of viral transcripts showed relatively high NRF2 activity as deduced from high NQO1 RNA velocity suggesting that NRF2 is activated as a part of the cellular defense against the progressing infection." (PMID 31653857, 2019). "Still, the anti-correlation of NQO1/SULF1 and the low transition probability of cells with high NQO1 levels into infection was observed." (PMID 31653857, 2019). "ML385 incubation reduced the levels of nqo1 mRNA in MGO-treated BMM at 4 and 24h after infection." (PMID 40602278, 2025). "The mRNA and protein expression of NQO1 and GCLC decreased at 5 h post-infection." (PMID 41413615, 2025). "Western blotting assays revealed that the 0.5 mM SA treatment led to a time-dependent upregulation of NRF2, HO-1, and NQO-1 protein expression, suggesting that SA may exert an antioxidative effect by activating the NRF2 signaling pathway after Mm infection." (PMID 38399751, 2024). "Moreover, infection of Vero hTMPRSS2 cells with SARS-CoV-2 decreased levels of Heme Oxygenase 1 (HO-1) and NAD(P)H quinone oxidoreductase 1 (NQO1) induced by Nrf2." (PMID 36009328, 2022). "Differences in expression level of NRF2 or Nqo1 between various L. spp. were not due to different levels of infection as we can conclude from S1C Fig." (PMID 33765083, 2021). "NQO1 expression was increased after mycobacterial infection, and NQO1 knockdown increased macrophage differentiation, NF-κB activation, and the secretion of pro-inflammatory cytokines TNF-α and IL-1β in response to infection." (PMID 27297123, 2016). "Of the four KSHV genes, only transduction with ORF71 (vFLIP) significantly upregulated NQO1 and HO1 mRNA expression, suggesting that vFLIP might be an important inducer of Nrf2 activity during later stages of infection." (PMID 25340789, 2014). "Additionally, the level of Nqo1 gene was also significantly reduced in Nox2-/- macrophages infected with LgyLRV1+ and LgyLRV1- but not in WT and Inos-/- cells at 8 hrs post-infection." (PMID 33765083, 2021).
neurodegenerative disease (17 papers, 2013 to 2025). A disorder of the central nervous system characterized by gradual and progressive loss of neural tissue and neurologic function. "In neurodegenerative diseases like Alzheimer’s, benfotiamine activates the transcription factor Nrf2, leading to increased expression of genes encoding antioxidant enzymes such as heme oxygenase 1 (HO-1) and quinone reductase 1 (NQO1)." (PMID 40647310, 2025). "In addition, NQO1 inactivation has been linked to many pathological conditions including cardiovascular diseases, cancer, metabolic disorders and several neurodegenerative diseases including Alzheimer’s disease." (PMID 36267290, 2022). "The present findings suggest that possibility that, by enhancing mitochondrial bioenergetics and reducing oxidative stress, up-regulation of NQO1 might protect neurons against pathogenic processes in neurodegenerative diseases including AD and PD." (PMID 23874855, 2013). "The NAD+/NADH ratio, regulated by NAD(P)H: Quinone Oxidoreductase 1 (NQO1), is closely linked to aging and neurodegenerative diseases." (PMID 40643498, 2025). "Clinical trials to examine CQ and its analogues as disease-modifying treatments against neurodegenerative diseases were mostly undertaken in Europe and Australia, where most participants would likely carry the stable C/C NQO1 genotype." (PMID 36267290, 2022). "In particular, NQO1 can be a good therapeutic target for neurodegenerative diseases, including AD, because it is an inducible enzyme responsible for 2-electron transfer without the production of semi-quinone radicals." (PMID 35052511, 2021). "Nrf2 activation initiates phase II enzymes expressions, such as heme oxygenase-1 (HO-1) and NADPH quinone oxidoreductase 1 (NQO1), which mitigates the pathogenesis of neurodegenerative diseases." (PMID 31010422, 2019). "Importantly, if CQ or its derivatives are to be used safely for the treatment of neurodegenerative diseases, it seems imperative that NQO1 levels and activity of prospective patients should be ascertained." (PMID 36267290, 2022). "We examined whether the ApoE‐dependent recovery induced by EA involves the Nrf2/ NQO1/HO‐1 signaling pathway, which mitigates oxidative stress in certain neurodegenerative diseases." (PMID 34423582, 2021). "In brain tissue, NQO1 is found abundantly in astrocytes and endothelial cells, is neuroprotective against oxidative damage in vivo and in vitro, and has increased activity in neurodegenerative diseases, such as Parkinson’s and Alzheimer’s." (PMID 30577502, 2018). "Elevating NAD+ level and ATP production without further ROS production, through NQO1 activation can be a good target for many neurodegenerative diseases." (PMID 35052511, 2021). "The results of the present study with regard to certain oxidative stress-related proteins (transferrin, ferritin, HO1, and NQO1) suggest that JGT could help to reduce neuroinflammation-related events and neuronal cell death in some neurodegenerative diseases." (PMID 30891075, 2019).
adenocarcinoma (10 papers, 1995 to 2025). A common cancer characterized by the presence of malignant glandular cells. "A point mutation in the mRNA of NADP(H): quinone oxidoreductase 1 (NQO1, DT-diaphorase) is believed to be responsible for reduced enzyme activity in the adenocarcinoma BE cell line." (PMID 7669561, 1995). "This study has shown high expression of NQO1 in the respiratory epithelium in a closely-related adenocarcinoma cohort." (PMID 36359002, 2022). "In vivo efficacy of CBK77 was validated by reduced growth of NQO1-proficient human adenocarcinoma cells in nude mice treated with CBK77." (PMID 34615851, 2021). "IHC staining consistently showed that the NQO1 protein was located in the cytoplasm of lung SCC and adenocarcinoma." (PMID 25880877, 2015). "For adenocarcinoma specifically, DM was observed in promoters [hypermethylated RASL12; SPTAN1, mir-26a, hypomethylated NQO1, SIRPB1, NF1A] and gene bodies [hypermethylated AKAP13, ANK family, PRKCE, ROS1; hypomethylated FAM171A1, PARK2, BCAS3, RHOJ] and many others." (PMID 26683690, 2015).
cardiovascular disease (9 papers, 2017 to 2025). "Genetic polymorphisms and reduced expression of NQO1 have been linked to an increased risk of cardiovascular diseases, underscoring its importance in cardiovascular health." (PMID 39338163, 2024). "Additional studies are required in order to determine the underlying mechanisms and protective effects of NQO1 in various types of cardiovascular disease." (PMID 34947831, 2021). "NQO1, which regulates cell cycle progression at the G2/M phase, is not active in non-replicating cardiac tissue, but is associated with cellular senescence, which can lead to cardiovascular disease." (PMID 39150892, 2024). "Other signaling pathways, such as Nrf2, may also be associated with the effects of NQO1 on cardiovascular diseases." (PMID 34947831, 2021). "In this context, continued mechanistic studies of the molecular regulation and biochemical activities of NQO1 will present additional insights into the importance of this phase-II protein in health and cardiovascular disease." (PMID 34947831, 2021). "Cardiovascular disease prevalence was higher in CKD 1–5 patients with higher compared to those with lower NQO1 gene expression (p = 0.02)." (PMID 28785379, 2017). "NQO1 plays a significant protective role in cardiovascular health by maintaining redox homeostasis and mitigating oxidative damage, which are essential to preventing cardiovascular diseases such as atherosclerosis, hypertension, and myocardial infarction." (PMID 39338163, 2024). "Numerous studies have shown that Nrf2 downstream targets, such as NQO-1, CAT, and SOD, have significant antioxidant effects on various cardiovascular diseases." (PMID 31934264, 2019). "Therefore, we investigated a relation between the NQO1 gene expression as a measure for NRF2 pathway activity and cardiovascular disease (CVD) prevalence in patients with non-dialysis-dependent CKD." (PMID 28785379, 2017).
neurological disorders (9 papers, 2019 to 2025). "The relationship between NQO1 polymorphisms and neurological disorders is complex and depends on the specific polymorphism and the genetic background of patients." (PMID 38167027, 2024). "Different polymorphisms in the NQO1 gene influence the translation of the NQO1 protein and contribute to the occurrence of various neurological diseases." (PMID 38167027, 2024). "NQO1 polymorphism C609T is also associated with enhanced risk of different neurological diseases, such as AD, MS, and Parkinson's disease (PD), presumably via destabilization of FAD affinity and enzyme stability." (PMID 38167027, 2024). "NQO1 polymorphisms are associated with an increased risk of some neurological disorders, such as MS and AD, likely due to structural and functional alterations of NQO1 and disruption in the cellular antioxidant defence." (PMID 38167027, 2024). "This study emphasizes the potential of NQO1 as a biomarker in diagnostic and prognostic approaches, as well as its suitability as a target for drug development strategies in neurological disorders." (PMID 38167027, 2024). "Finally, we discussed the challenges in designing and developing novel substances that target NQO1 for diagnostic, preventive, and therapeutic purposes in neurological disorders." (PMID 38167027, 2024). "Available data strongly suggest that targeting NQO1 could be a promising strategy for developing new diagnostic and therapeutic compounds for neurological disorders." (PMID 38167027, 2024). "Moreover, we provided a comprehensive review of the current experimental and clinical knowledge of the potential prognostic, diagnostic, and therapeutic roles of the NQO1 in different neurological disorders." (PMID 38167027, 2024). "This is in agreement with previous reports highlighting alterations of NQO1 in the brain and linking those changes to the pathophysiology of neurological disorders." (PMID 41109135, 2025). "The precise mechanisms through which abnormalities in NQO1 function contribute to these neurological disorders continue to be a subject of ongoing research." (PMID 38167027, 2024). "Numerous investigations have evaluated the potential role of NQO1 in the development and progression of various neurological disorders." (PMID 38167027, 2024). "Understanding the function of NQO1 and its modulatory role in the CNS is crucial for revealing its potential therapeutic implications in various neurological disorders." (PMID 38167027, 2024). "Building upon the existing knowledge, the present study reviews current investigations describing the role of NQO1 dysregulations in various neurological disorders." (PMID 38167027, 2024). "In the past few years, significant progress has been made in uncovering the pathological roles of NQO1 in various neurological disorders." (PMID 38167027, 2024). "Among multiple antioxidant enzymes, SOD, HO-1, and NQO1 were extensively studied in hippocampal neurons and neurological disorders." (PMID 35993019, 2022). "Furthermore, NQO1 can be utilized as a biomarker for tracking subtle changes in neural tissues and serve as an early warning system for the emergence of neurological diseases." (PMID 38167027, 2024). "Studies on different in vitro experimental models suggest that NQO1 and C/EBP may exert bidirectional regulatory interactions on each other and modulate cell proliferation and differentiation in some neurological disorders." (PMID 38167027, 2024).
metabolic disorders (7 papers, 2015 to 2022). "In short, transport stress-induced NO-NOS system metabolic disorders and heart oxidative stress are mitigated by activating the Nrf2/HO-1/NQO1 antioxidant defense response in newborn chicks." (PMID 35754548, 2022). "Despite the important role of oxidative stress in metabolic diseases, the associations of HMOX1 and NQO1 with MetS have not yet been thoroughly studied." (PMID 25933176, 2015).
hematological disease (4 papers, 2018 to 2024). "Furthermore, mutated NQO1*2 is degraded rapidly by the 26S proteasome, and a deficiency in NQO1 makes cells more susceptible to benzene, which is a risk factor for hematological malignancy." (PMID 32645959, 2020). "Intriguingly, in comparison to the previous analysis, we observed 6 new non-synonymous SNVs linked to hematological disease, including variations in CBL (1 pt); DNMT3A (3 pts); FLT3 (1 pts), NQO1 (1 pt); NRAS (1 pts) and 2 frameshifts: CEBPA (1 pts) and NBN (1 pts)." (PMID 38612443, 2024). "Therefore further research is required to explore the impact of NQO1 on hematological malignancies." (PMID 37583897, 2023). "In addition, hematological disorders may also be related to polymorphisms in genes encoding xenobiotic-metabolizing enzymes, such as cytochrome P4502E1 (CYP2E1), myeloperoxidase (MPO), NAD(P)H:quinone oxidoreductase 1 (NQO1), and glutathione S-transferase (GST)." (PMID 30154939, 2018).
inflammation (3 papers, 2014 to 2024). Aberrant reaction of the microcirculation characterized by movement of fluid and leukocytes from the blood into extravascular tissues. "In conclusion, CND can inhibit TNF-α-induced endothelial inflammation, possibly due to its direct scavenging of H2O2 and the indirect upregulation of antioxidant enzyme NQO1 activity in endothelial cells." (PMID 38397822, 2024).
bacterial infection (2 papers, 2022 to 2025). "Viral and bacterial infection of lung organoids have demonstrated functional impact of small molecule inhibitors or pathway activators, including NAD(P)H dehydrogenase quinone 1 (NQO1) with antibiotic cefoxitin or anti-viral Remdesivir to understand mechanisms or drug efficacy." (PMID 40966450, 2025).
colon (2 papers, 2021 to 2022). "The digestive system cancer had a weaker correlation with NQO1 rs1800566 polymorphism, which were classified malignancies into six different systems." (PMID 36338728, 2022).
central nervous diseases (1 paper, 2024). "Increasing evidence suggests the protective role of the Nrf2-ARE signal pathway in central nervous diseases mediated by heme oxygenase-1 (HO-1) and NQO1." (PMID 38167027, 2024).